WBP2 (WW domain binding protein 2)
Diseases named in the same sentence as WBP2 in open-access papers (continued):
Sharing a sentence is not in itself a finding about the gene and the disease.
tumor (continued). "We attempted to determine whether WBP2 impacts the malignant phenotype of tumor cells in NSCLC." (PMID 33837178, 2021). "In conclusion, we demonstrated that WBP2 drives TNBC migration and invasion under TNF‐α‐induced conditions, which mimic the tumor‐stimulatory microenvironment." (PMID 34197030, 2022). "In non-tumor cells, MCF-10A and NIH3T3, the binding of WBP2 and TAZ is vital for cell proliferation." (PMID 33837178, 2021). "Reciprocally, WBP2 itself can be modulated by the Hippo kinase MST, signifying a positive feedback loop to turn on the switch toward carcinogenesis and tumour malignancy." (PMID 34831354, 2021). "The PR domain of WBP2 ranks among a wide diversity of YAP ligand binding sites and the YAP–WBP2 interaction has also been reported to participate in the Hippo tumor suppressor pathway." (PMID 28724435, 2017). "When WBP2 binds with WWOX, a tumor suppressor, ER transactivation and tumor growth can be suppressed." (PMID 28724435, 2017). "WBP2 is an emerging tumor protein that functions in different oncogenic signaling pathways, such as the ER/PR, EGFR, PI3K, Hippo, and Wnt signaling pathways, and WBP2 has gained attention as a potential drug target." (PMID 38239300, 2024). "Samples without corresponding vales for WBP2 mRNA or protein z‐scores in each tumor types were not considered in the analysis." (PMID 34197030, 2022). "Our study positions miR-23a as a potential tumor suppressor by virtue of its negative effect on WBP2 expression." (PMID 32820148, 2020). "Although previous studies hinted the possible involvement of WBP2 in inflammation, via its binding to ITCH, a negative regulator of TNF/NF‐κB signaling, this study shows for the first time a participatory role of WBP2 in tumor inflammatory signaling, particularly in TNF/NF‐κB signaling pathway." (PMID 34197030, 2022).
infection (2 papers, 2023 to 2024). The state of being infected such as from the introduction of a foreign agent such as serum, vaccine, antigenic substance or organism. "WBP2 is a gene involved in many signaling pathways, including the PI3K/Akt/mTOR signaling pathway, and has been shown to be downregulated in pig macrophages after infection with porcine reproductive and respiratory syndrome virus." (PMID 37872508, 2023).
adenocarcinoma (1 paper, 2021). A common cancer characterized by the presence of malignant glandular cells. "Cox univariate and multivariate analyses indicated that a high TNM stage, adenocarcinoma histological type, and high WBP2 expression (P = 0.038, P = 0.017, and P = 0.030, respectively) were all independent prognostic factors in NSCLC." (PMID 33837178, 2021).
WBP2 also shares sentences with these, for which no sentence is quoted: Hearing impairment (2 papers); non-small cell lung carcinoma (2); acute myeloid leukemia (1); alcoholism (1); autism (1); benign tumors (1); brain cancer (1); breast (1); breast tumours (1); diabetes (1); hematological disorders (1); Infertility (1); inherited genetic diseases (1); lung adenocarcinoma (1); malignant carcinomas (1); melanoma (1); neurological disorders (1); squamous cell carcinoma (1); systemic lupus erythematosus (1); thyroid (1); uterine cancer (1); uterine carcinosarcoma (1); uveal melanoma (1).